NFKB1 (nuclear factor kappa B subunit 1)
Diseases named in the same sentence as NFKB1 in open-access papers (continued):
Sharing a sentence is not in itself a finding about the gene and the disease.
multiple myeloma (438 papers, 2005 to 2025). "Bortezomib, a proteasome inhibitor of the NFKB1 - regulated inflammatory pathway, is widely used to treat multiple myeloma." (PMID 40313558, 2025). "Although genome-wide surveys have detected NFKB1 rearrangements in myeloma (e.g. PIM2::NFKB1) and have exhaustively catalogued IGH translocation partners, an IGH::NFKB1 fusion has never been reported, supporting the novelty of the alteration described here." (PMID 41200196, 2025). "The importance of the NFκB pathway in multiple myeloma is further highlighted by genetic or epigenetic alterations found in other genes in this pathway, such as NIK, TRAF3, CD40, NFKB1, or NFKB2." (PMID 33327527, 2020). "We therefore conclude that this is the first documented case of PLNEMP that evolved into “myeloma-like” bone destruction while retaining minimal marrow involvement, a trajectory underscored by the novel IGH::NFKB1 fusion identified by comprehensive molecular profiling." (PMID 41200196, 2025). "Importantly, among the upregulated genes, there were several genes encoding established pro-survival and anti-apoptotic factors in myeloma, including MYC, IRF4, NFKB1/2, BCL2, and BCL2L1." (PMID 38911853, 2024). "Recently, genetic alterations in components of the noncanonical and canonical NF-κB pathways (e.g., NIK, TRAF3, CYLD, BIRC2/BIRC3, CD40, NFKB1, or NFKB2) resulting in their activation have been identified in multiple myeloma." (PMID 18596915, 2008).
autoimmune disease (419 papers, 2006 to 2026). A disorder resulting from loss of function or tissue destruction of an organ or multiple organs, arising from humoral or cellular immune responses of the individual to their own tissue constituents. "In addition, recent cohort studies on patients with NFKB1 variants have shown that infections, lymphoproliferative disorders, autoimmune diseases, and malignancies are the most common and age-dependent manifestations in these patients." (PMID 35003082, 2021). "NFKB1 is also genetically associated with autoimmune disease Ulcerative colitis." (PMID 29325558, 2018). "Resistin is implicated in cardiovascular, metabolic, and autoimmune diseases, as it affects molecular pathways associated with inflammation, including the activation of NFKB1 nuclear factor kappa B (NF-kB) by Toll-like receptor 4 (TLR4)." (PMID 39335642, 2024). "Investigating the TFs regulating the fine‐mapped autoimmune disease enhancers, we find the known immune response TFs NFKB1/2, RELB and IRF8, but also MBD2, ZBT14 and PURA, which we identified as important TFs for predicting response to infection." (PMID 37073532, 2023). "Single nucleotide polymorphisms (SNPs) in the GTFSI, NFKB1, and TYK2 genes have been reported to be associated with SSc in other populations and in individuals with various autoimmune diseases." (PMID 34248934, 2021). "Among 23 prioritized genes, we found 14 genes with known drug indications on other autoimmune diseases as well as 2 genes (NFKB1, SH2B3) with indications on other diseases." (PMID 32879140, 2020). "Transcription factors NFKB1 and RFX5 are each associated with three and six autoimmune disorders, while both TFs are known to be involved in autoimmunity." (PMID 29325558, 2018). "Interestingly, the lead SNP at the MANBA/UBE2D3 locus, rs223486, is an intergenic variant located in a region (±500 kb) that harbors several other genes (CISD2, NFKB1, SLC9B1/2, BDH2 and CENPE) with reported inflammatory and autoimmune disease associations." (PMID 33402679, 2021). "Moreover, we predicted potential drug targets for autoimmune diseases, including 2 genes (NFKB1 and SH2B3) with known drug indications on other diseases, highlighting their potential drug repurposing opportunities." (PMID 32879140, 2020). "Other variants in NFKB1 in CVID have been described as the most common cause of CVID with non-infectious complications, including lymphadenopathy, splenomegaly, and autoimmune disease, and all reported patients exhibit deficient B-lymphocyte differentiation with increased CD21low B-cell numbers." (PMID 32047491, 2019). "Considering the genetic overlap of autoimmune diseases and the association of these genes with SSc in other populations, we hypothesized that some of the related tag SNPs of GTF2I, NFKB1, and TYK2 may also contribute to susceptibility to SSc in the Chinese Han population." (PMID 34248934, 2021). "Together, our analysis not only prioritized some new promising drug targets for future drug exploration, but also suggested some known drug targets (NFKB1, SH2B3) that could be exploited for future drug repurposing on autoimmune diseases." (PMID 32879140, 2020). "The clinical spectrum of NFKB1 LOF includes massive lymphadenopathy (24%), unexplained splenomegaly (48%), and autoimmune disease (48%), either organ-specific and/or hematologic in nature (mainly autoimmune hemolytic anemia and idiopathic thrombocytopenic purpura, see Tables E1 and E2)." (PMID 29477724, 2018).
inflammatory bowel disease (409 papers, 2005 to 2026). A spectrum of small and large bowel inflammatory diseases of unknown etiology. "Existing evidence identifies NFKB1 as a causal gene in the pathogenesis of inflammatory bowel diseases." (PMID 36619207, 2022). "Another observation is that all four genome-wide significant risk loci (PLA2R1, IRF4, NFKB1, and HLA) exhibit highly pleiotropic effects and all four lead SNPs have a concordant effect on the risk of inflammatory bowel disease (IBD)." (PMID 32231244, 2020). "The -94 insertion/deletion ATTG polymorphism was identified in a study sequenced the NFKB1 promoter in 10 inflammatory bowel disease and 2 controls, and the ATTG1 allele was more frequent in ulcerative colitis than that in controls in the following study." (PMID 19480714, 2009). "In contrast, chromatin at a risk locus within the intragenic region of NFKB1, which is associated with non-CNS autoimmune diseases (inflammatory bowel disease and systemic scleroderma), was accessible only in T cells, but not in astrocytes." (PMID 30559390, 2018). "Furthermore, polymorphisms in genes encoding TLR2 and NF-κB signaling proteins (NFKB1 and NFKBIA) are associated with risk of inflammatory bowel disease (IBD)." (PMID 27563173, 2016).
leukemia (389 papers, 2005 to 2026). A malignant (clonal) hematologic disorder, involving hematopoietic stem cells and characterized by the presence of primitive or atypical myeloid or lymphoid cells in the bone marrow and the blood. "DBF activates the expression of genes encoding the proteins involved in leukemia cell survival, such as KIT, CTNNB1, CCNE1, NFKB1, E2F1, and downregulates the expression of CCND2, CCNA1, and FLT3 genes." (PMID 34564151, 2021). "Nfkb1+/− TCL1 mice still show a significant reduction in leukemia incidence, demonstrating that even a partial reduction in Nfkb1 can impede disease development." (PMID 30205516, 2018). "In our study, HQ exposure upregulated the mRNA level of NFKB1 in chronic myeloid leukemia and acute myeloid leukemia pathway, which partly supported that HQ might promote leukemia development by activating the NF-κB pathway." (PMID 35366954, 2022). "In addition, Nfkb1-deficient leukemic cells presented a cell surface marker phenotype (expression of variable levels of CD4, CD8, CD24, CD25, and TCRβ/CD3ε) similar to that of Nfkb1-proficient cells (data not shown) and characteristic of transgenic TEL-JAK2 leukemia." (PMID 18596915, 2008).
Arthritis (386 papers, 2005 to 2026). Inflammation of a joint. "The very high point that NFKB1 obtained from the keyword query was in part due to the word 'arthritis' appearing in the corresponding OMIM text." (PMID 15899035, 2005).
endothelial dysfunction (374 papers, 2008 to 2026). In vascular diseases, endothelial dysfunction is a systemic pathological state of the endothelium (the inner lining of blood vessels) and can be broadly defined as an imbalance between vasodilating and vasoconstricting substances produced by (or acting on) the endothelium. "The rs28362491 (-94ATTGins/del) polymorphism of the NFKB1 gene has been reported in shear-induced eNOS gene expression and endothelial dysfunction in prehypertension and stage I hypertension, mostly due to differences in NFKB1 gene transcriptional activity." (PMID 30910844, 2019). "Our precious study also reported that mutant DD genotype of rs28362491 in NFKB1 gene was a accompanied with endothelial dysfunction and higher inflammatory status in CAD patients." (PMID 30910844, 2019).
depression (359 papers, 2008 to 2026). "Mounting evidence underscores the intricate interplay between depression and inflammation, with studies revealing elevated levels of inflammatory markers, such as tumor necrosis factor α (TNF-α) and nuclear factor kappa B subunit 1 (NF-κB1), in individuals with depression." (PMID 39851527, 2025). "Furthermore, differences between MDD and BPD were seen for matrix-associated growth factors APP and SPARC, immune gene TNF, and transcription factors CREB1, NFKB1, and NR3C1 when controlling for depression severity, age, and medication use." (PMID 24143878, 2013).
cervical carcinoma (313 papers, 2005 to 2026). A carcinoma arising from either the exocervical squamous epithelium or the endocervical glandular epithelium. "NFKB1 enhanced the sensitivity of cervical cancer cells to the effects of irradiation, and the mutation in NFKB1 weakened this effect." (PMID 29484114, 2018). "Taken together, it was reasonable that NFKB1 and its mutations play an important role in cervical cancer, which was caused by HPV infection." (PMID 29484114, 2018). "To further investigate the effect of NFKB1 and NFKB1 mutation G430E on cervical cancer cells with radiation, we overexpression wild-type and mutant (G430E) NFKB1 in Hela cells (HPV-18 positive-cell), and the cells were then irradiated." (PMID 29484114, 2018). "We also found that overexpression of NFKB1 enhanced the sensitivity of cervical cancer cells to the effects of irradiation, and the mutation in NFKB1 weakened this effect." (PMID 29484114, 2018). "Further functional assays showed that NFKB1 was a tumour suppressor in cervical cancer by inhibiting cell proliferation, colony formation and migration, while the mutation in NFKB1 could weaken the tumour suppressing functions of NFKB1." (PMID 29484114, 2018). "Further functional assays showed that NFKB1 was a tumour suppressor in cervical cancer, and the mutation in NFKB1 could weaken the tumour suppressing functions of NFKB1." (PMID 29484114, 2018). "NFKB1 could enhance the sensitivity of cervical cancer cells to the irradiation, and the mutation in NFKB1 weakened this effect." (PMID 29484114, 2018). "Moreover, NFKB1 was a tumor suppressor by inhibiting cell proliferation, colony formation and migration in cervical cancer, while the mutation could weaken the tumor-suppressing function of NFKB1." (PMID 34321012, 2021). "Thus, NFKB1 and its mutation may be a potential molecular target in cervical cancer radiation therapy in the future." (PMID 29484114, 2018). "Our findings indicated that compounds of Solanecio mannii aqueous roots extract offer a promising strategy for the management of cervical cancer through targeting NFKB1." (PMID 40446016, 2025). "Compared with empty vector, overexpression of wild-type NFKB1 further inhibit the survival of cervical cancer cells with irradiation." (PMID 29484114, 2018). "In summary, NFKB1 plays important roles in the regulation of tumorigenesis and malignant progression in cervical cancer." (PMID 29484114, 2018). "While compared with wild-type NFKB1, mutant NFKB1 (G430E) promoted the survival of cervical cancer cells with irradiation." (PMID 29484114, 2018). "We further demonstrated that this mutation (G430E) could weaken the tumour suppressing functions of NFKB1 and could promote the survival of cervical cancer cells following irradiation." (PMID 29484114, 2018). "Therefore, targeting NFKB1 is a promising approach for the management of cervical cancer." (PMID 40446016, 2025). "By analyzing the differential expression of CXC chemokines in cervical cancer, we identified three key transcription factors (RELA, NFKB1 and SP1)." (PMID 34321012, 2021).
diabetic nephropathy (304 papers, 2009 to 2026). "Translocation of NFKB1 to the nucleus and binding to promoters of many genes facilitates diabetic nephropathy progression." (PMID 40533788, 2025).
Stroke (300 papers, 2006 to 2026). Sudden impairment of blood flow to a part of the brain due to occlusion or rupture of an artery to the brain. "The stroke insult-related genes were Nfkb1, histone deacetylase 2 (Hdac2), and sirtuin 1 (Sirt1) in the vs. MCAO+tDCS-FN(cA) and U2 small nuclear RNA auxiliary factor 2 (U2af2) in the vs. MCAO+tDCS-FN(iC-cA) configurations." (PMID 38389833, 2024). "In the stroke group, the Nfkb1 gene (0.1601-fold) was strongly induced, compared to the control group (0.0066-fold)." (PMID 39338346, 2024). "Triflusal, a treatment for stroke re-occurrence, targets four genes (PTGS1 (also known as Cox-1), NOS2, NFKB1, and PDE10A) that together have more functional variants in the African population than in any other population (DRPAFR = 37%)." (PMID 29273096, 2017). "We observed a sex-specific downregulation of other chemokines and Nfkb1 upon MMP-3 deletion, but this was unsurprising considering well-established sex differences in the inflammatory response to stroke." (PMID 39000490, 2024). "Genes related to inflammation such as Ccl5, Cxcl5, Il1a, Tnfsf10, Nfkb1, Tnfrsf1b, Ccr7, Tnfrsf9, Ccl7, Il1b, Il6, and Ccl24 were also downregulated upon MMP-3 KO in male stroke brains." (PMID 39000490, 2024).
ulcerative colitis (298 papers, 2008 to 2026). An inflammatory bowel disease involving the mucosal surface of the large intestine and rectum. "The NFKB1 gene rs28362491 polymorphism was first reported to be a susceptible factor for ulcerative colitis in 2004." (PMID 36317060, 2022). "NFKB1 is a transcription factor is involved in many immune- and tumor-related processes, and has been associated with ulcerative colitis and bladder cancer." (PMID 30679814, 2019). "The deletion allele was initially associated with an increased risk for ulcerative colitis and would be linked to reduced expression of NFKB1 compared to the insertion allele." (PMID 31815120, 2019). "Previous studies have shown that the rs28362491 (-94ATTGins/del) polymorphism of the NFKB1 gene was associated with many inflammatory diseases such as Grave’s disease, ulcerative colitis, and systemic lupus erythematosus." (PMID 30910844, 2019). "They demonstrated that the NFκB1/p50 promoter containing the -94delATTG allele was less active than that containing the -94insATTG allele, and was associated with susceptibility to ulcerative colitis." (PMID 28350359, 2017). "In 2004, Karban AS first indicated that NFKB1 -94delATTG allele showed less promoter activity than comparable constructs containing the -94insATTG allele, and this genetic variant was associated with ulcerative colitis." (PMID 30910844, 2019). "Previous studies reported that -94 ATTG deletion mutant (DD genotype) in promoter of the NFKB1 gene (rs28362491) was associated with inflammatory diseases, including CAD, inflammatory bowel disease, and ulcerative colitis." (PMID 36317060, 2022).
renal fibrosis (286 papers, 2013 to 2026). A final common manifestation of a wide variety of chronic kidney diseases characterized by glomerulosclerosis and tubulointerstitial fibrosis. "In mouse kidneys with fibrosis and inflammatory infiltration, sample sequencing to a depth of 30 million reads and network analysis showed that the top TFs, such as Irf1, Nfkb1, and Stat3, are important drivers of renal fibrosis progression." (PMID 36246123, 2022). "Meanwhile, NFKB1 was highly expressed in renal fibrosis samples from the GSE36496 dataset." (PMID 35672285, 2022).
ischemia (260 papers, 2009 to 2026). A hypoperfusion of the BLOOD through an organ or tissue caused by a PATHOLOGIC CONSTRICTION or obstruction of its BLOOD VESSELS, or an absence of BLOOD CIRCULATION. "It is important to note that ischemia-induced astroglial NF-κB may have neurodegenerative effects, whereas constitutive neuronal nuclear factor kappa B subunit 1 (NFΚB1) may have neuroprotective effects." (PMID 34829993, 2021).
Alzheimer disease (259 papers, 2010 to 2026). A progressive, neurodegenerative disease characterized by loss of function and death of nerve cells in several areas of the brain leading to loss of cognitive function such as memory and language. "These targets were found to be related to metabolite interconversion enzymes, modified residues, regulation of apoptotic signaling pathway, “Alzheimer’s Disease, Focal Onset”, NFKB1, SP1, and RELA, hsa-miR-17-5p, hsa-miR-16-5p, and hsa-miR-26b-5p." (PMID 39493676, 2024). "“Acute Confusional Senile Dementia”, “Alzheimer’s Disease, Focal Onset”, NFKB1, SP1, and RELA were found to be the most important diseases and transcription factors." (PMID 39493676, 2024). "In RT-PCR assays, pre-treatment with GLE decreased mRNA expression of CHUK, NFκB1/p150, and IKBKE (NFƙB signaling), which may be associated with the neuropathology of Alzheimer’s disease." (PMID 32480240, 2020).
ischemic stroke (259 papers, 2010 to 2026). A stroke disorder caused by obstruction of blood flow to the brain, due to thrombotic (local blood clot formation) or embolic (due to a blood clot or other material traveling from another site) event. "A recent study has indicated that the polymorphisms in NFKB1 promoter can modulate the susceptibility to ischemic stroke." (PMID 34483854, 2021). "Our results showed that Nfκb1 was significantly up-regulated in ischemic stroke rats with QDBS rather than YDBS." (PMID 29340078, 2017).
periodontitis (257 papers, 2010 to 2026). An acute or chronic inflammatory process that affects the tissues that surround and support the teeth. "We aim to identify the diagnostic potential of NFKB1, hsa-miR-(342–5192, and 15b) in serum as well as gingival crevicular fluid (GCF) in individuals with T2DM+chronic periodontitis." (PMID 41731468, 2026). "CONCLUSIONS: NFKB1 and miRNAs hsa-miR-342-5p -5192, and − 15b exhibit strong potential biomarkers for diagnosing periodontitis and T2DM-associated periodontitis." (PMID 41731468, 2026). "Nuclear factor kappa B p105 subunit (NFKB1), instead, which is considered as a leader gene in periodontitis, was assigned to cluster C in the present study." (PMID 32962181, 2020). "Of the top 10 hub TFs, six “leader” immunosuppressive TF-target DEGs with plausible literature evidence were identified as key to periodontitis pathogenesis and included the down-regulated TFs (NFKB1, FOS, and JUN), as well as up-regulated TFs (HIF1A, STAT5B, and STAT4)." (PMID 33777111, 2021). "RESULTS: Levels of NFKB1 and the selected miRNAs were significantly heightened in T2DM with periodontitis cases compared to controls." (PMID 41731468, 2026). "Transcriptomic network analysis has identified transcription factors (TFs), including NF-κB (NFKB1/RELA), AP-1 (FOS/JUN), and STAT3, as master regulators in periodontitis, highlighting their recent relevance." (PMID 41050338, 2025).